XIAP (X-linked inhibitor of apoptosis)
Diseases named in the same sentence as XIAP in open-access papers (continued):
Sharing a sentence is not in itself a finding about the gene and the disease.
lung adenocarcinoma (9 papers, 2013 to 2025). A carcinoma that arises from the lung and is characterized by the presence of malignant glandular epithelial cells. "Sestrin2 stimulated lysosomal degradation of X-linked inhibitor of apoptosis protein (XIAP) to promote receptor-mediated apoptosis of lung adenocarcinoma cells." (PMID 35527284, 2022). "For example, Chl. could induce a decrease in the viability of A549 (a non-small-cell lung cancer cell line) and CL1–5 (a lung adenocarcinoma cell line) via mitochondria-mediated apoptosis by down-regulating B cell lymphoma 2 (Bcl-2) (Bcl-2), X-linked inhibitor of apoptosis (XIAP), and surviving." (PMID 40933734, 2025). "Dysregulation of XIAP has been shown to affect the progression of a variety of cancers, including lung adenocarcinoma (LUAD)." (PMID 35992856, 2022). "However, the function and mechanisms of XIAP in lung adenocarcinoma with brain metastasis (LUAD-BM) remains poorly understood." (PMID 35992856, 2022). "However, in contrast to lung adenocarcinoma cells in which Bim appears to play the major role in the synergized apoptosis, XIAP, Mcl-1 and Bim all contributed to the synergized apoptosis in RCC cells." (PMID 23387989, 2013). "A549 lung adenocarcinoma cells overexpressing mutant KEAP1 showed high TRAF2-mediated NFκB activity and increased protection against apoptosis, XIAP being one of the key proteins involved in anti-apoptotic signalling." (PMID 38184997, 2024). "For instance, circ_0000527/miR-98-5p/XIAP facilitates the malignant progression of retinoblastoma cells, and circ_0018414/miR-6807-3p/DKK1 impedes the tumor development in lung adenocarcinoma." (PMID 34421997, 2021). "XIAP protein over-expression has been identified in six NSCLC cell lines and its inhibition triggers apoptosis in human lung adenocarcinoma A549 cells." (PMID 23874428, 2013). "Some of the genes such as PIK3CA, TAF15, VAPB, Appl1, Rab5a, ARF4, and XIAP in Merged-module activate the PI3K-Akt pathway and are overexpressed in a manner similar to that of EGFR in lung adenocarcinoma." (PMID 23874428, 2013).
viral infection (9 papers, 2016 to 2025). "XIAP deficient patients are characterized with multi-organ inflammation triggered by viral infections, as well as intestinal bowel disease." (PMID 31541082, 2019). "The stable introduction of XIAP WT genes by viral infection decreased HCT116 cell growth more than the introduction of CTL and XIAP S406A genes." (PMID 32994395, 2020). "Notably, both factors exhibit vital functions in viral infections: GADD45 restricts HIV-1 replication by suppressing viral transcription and negatively regulates JNK signaling through MKK7 targeting, whereas XIAP modulates Ripoptosome-mediated cell death via degradative inhibition." (PMID 41011363, 2025).
colitis (8 papers, 2017 to 2025). Inflammation of the colon. "A subset of patients with XIAP deficiency show early-onset colitis, severe failure to thrive, and splenomegaly/hepatosplenomegaly an increased risk of medically refractory IBD phenotype and increased mortality." (PMID 40218181, 2025). "Since defective interaction of XIAP mutants with RIP2 leading to defective NOD signaling causes the basic pathogenesis of colitis, understanding the altered phenomenon may be essential in studying refractory colitis with XIAP mutations." (PMID 38191507, 2024). "Besides colitis, other gastrointestinal manifestations have also been described in context of XIAP deficiency, including coeliac-like disease characterised by blunted villi and lymphocytic infiltrates, chronic diarrhoea and severe or chronic parasitic infections." (PMID 34222142, 2021). "A significant number of XIAP patients suffer from colitis, a disease manifestation that is observed less frequently in SAP deficient patients." (PMID 34222142, 2021). "In this subset, early HSCT with reduced intensity conditioning may result in both resolution of their colitis and reduction in their risk of developing HLH, which is the leading cause of mortality in XIAP-deficient patients." (PMID 40218181, 2025). "None of our seven patients with XIAP deficiency, or their carrier mothers, developed colitis or other intestinal manifestations; however, one patient suffered from diarrhea for 3 days and recovered soon after symptomatic treatment." (PMID 31754776, 2020). "In contrast, co-administration of Xiap−/− tTreg cells did not prevent the colitis-associated pathogenesis, suggesting that the absence of XIAP greatly diminished the suppressive activities of tTreg cells in vivo." (PMID 29386580, 2018). "Because XIAP deficiency is correlated with an elevated risk of mortality in patients with colitis and also with enhanced apoptosis in MAIT cells, it suggests that MAIT cells have a protective role in colitis." (PMID 29250077, 2017). "XIAP deficiency is now considered an important cause of IBD; however, in the present study, only 1 of 22 (4.5%) Chinese XIAP-deficient patients developed IBD, while no other patients or carrier mothers suffered from colitis or other intestinal manifestations." (PMID 31754776, 2020).
endometrial cancer (8 papers, 2009 to 2025). Primary or metastatic malignant neoplasm involving the endometrium (mucous membrane that lines the endometrial cavity). "XIAP (X-linked inhibitor of apoptosis protein) plays a key antiapoptotic role in endometrial carcinoma cells." (PMID 20712893, 2010). "In fact, XIAP protects endometrial cancer cells against various proapoptotic agents, including chemotherapeutic drugs." (PMID 28969018, 2017). "We have recently reported that exposure to each of the three TGF-β isoforms increase XIAP protein levels in endometrial carcinoma cells." (PMID 20712893, 2010). "This member of the inhibitor of apoptosis protein family can directly inhibit caspases-3, -7, and -9, and we recently observed that XIAP protects endometrial carcinoma cells against various proapoptotic agents, including TGF-β, TNFα and chemotherapeutic drugs." (PMID 20712893, 2010). "We have previously showed that exposure to each of the three TGF-β (transforming growth factor beta) isoforms upregulates XIAP protein content in endometrial carcinoma cells in vitro." (PMID 20712893, 2010). "We had previously shown that exposure to TGF-β isoforms increases XIAP protein content in endometrial carcinoma cells, and here we found that the three TGF-β isoforms upregulate XIAP expression, at the mRNA level, in these cells." (PMID 20712893, 2010). "It was shown that Akt phosphorylation is regulated by XIAP in human ovarian epithelial cancer cells and in rat granulosa cells and that phosphorylated Akt is affected by the presence of cIAP-1 in endometrial cancer cells." (PMID 19656380, 2009). "Furthermore, studies have shown that hnRNP A1 knockdown reduces BCLXL and XIAP expression in endometrial cancer cells, leading to apoptosis and inhibiting proliferation." (PMID 41285764, 2025). "In endometrial cancer, Esculetin promotes apoptosis and inhibits tumor cell proliferation by targeting hnRNP A1, which downregulates BCLXL and XIAP." (PMID 41285764, 2025). "Esculetin is a coumarin derivative that suppresses endometrial cancer proliferation and induces apoptosis by downregulating the BCLXL and XIAP via hnRNPA1." (PMID 35264951, 2022). "miR-214-3p is shown to modulate cell growth, metastasis, and apoptosis in HCC cells, endometrial cancer cells, and retinoblastoma cells by directly targeting certain genes linc00665, ATWIST1, BCB1, and XIAP." (PMID 36276270, 2022). "Our results suggested that TGF-β isoforms differentially activate intracellular signaling pathways in endometrial carcinoma cell: indeed, only TGF-β3 activates PI3-K/Akt pathway and increases XIAP protein levels in a PI3-K-dependent manner in these cells." (PMID 20712893, 2010). "Moreover, we have shown in our laboratory that TGF-β isoforms efficiently inhibit cellular proliferation in human endometrial carcinoma cell lines and that TGF-β3 increases invasiveness of endometrial carcinoma cells through PI 3-K upregulation of XIAP and protein kinase C induction of MMP-9." (PMID 19656380, 2009).
renal cell carcinoma (7 papers, 2004 to 2021). "Unbalanced expression between XIAP and Smac probably contributes to progression of renal cell carcinomas and results in marked apoptosis resistance of this tumour." (PMID 21645409, 2011). "Disturbed balance of expression between XIAP and Smac contributed to progression of renal cell carcinoma and XIAP was an independent prognostic biomarker of clear cell renal cell carcinoma." (PMID 21645409, 2011). "Studies have reported that the balance between XIAP and Smac/DIABLO expression is gradually disturbed during progression of renal cell carcinomas and testicular germ cell tumors." (PMID 19397802, 2009). "The aim of the present investigation, therefore, was to explore the relevance of XIAP and Smac/DIABLO expression for tumour progression in a large cohort of renal cell carcinomas (RCCs) of all major histological types." (PMID 15328523, 2004).
Arthritis (6 papers, 2015 to 2021). Inflammation of a joint. "In addition, uveitis and arthritis are now well-recognised manifestations of XIAP deficiency." (PMID 34222142, 2021). "Deficiency of all three IAPs (c1LysMcrex−/−c2−/− BM chimeras), but not XIAP and cIAP2, in the myeloid compartment led to accelerated and exacerbated K/B × N arthritis." (PMID 25693118, 2015). "On the same line, mice lacking IAPs, including XIAP, may critically contribute to the immunopathogenesis observed in arthritis or during γ-herpesvirus infection." (PMID 27735938, 2016).
chondrosarcoma (6 papers, 2009 to 2022). A malignant cartilaginous matrix-producing mesenchymal neoplasm arising from the bone and soft tissue. "Moreover, shikonin derivatives dose-dependently regulated the expression of X-linked apoptosis inhibitor (XIAP) in chondrosarcoma cells, leading to damage of mitochondrial membrane potential and subsequent induction of apoptosis." (PMID 35820864, 2022). "Inhibition of BMPR2 induces apoptosis and autophagy in human chondrosarcoma by destabilization of XIAP." (PMID 34903128, 2021). "Knockout of BMPR2 in chondrosarcoma with siRNA destabilized XIAP, increased tumor apoptosis, suppressed tumor growth, and increased autophagy." (PMID 30149506, 2018). "In the current study, we focused on how Smad-independent pathway, specifically XIAP, regulated the growth of chondrosarcoma cells, but the crosstalk between Smad-independent and -dependent pathway has not been well understood." (PMID 25501832, 2014). "Taken together, these results suggest that knockdown of BMPR2 reduced the level of XIAP through a Smad-independent pathway in chondrosarcoma cells." (PMID 25501832, 2014). "Based on these data, chondrosarcoma cells were treated with 10 μM of Bcl-2 inhibitor, 10 μM of C-4 (P-glycoprotein inhibitor) or 10 μM of embelin (XIAP inhibitor) and two different concentrations of doxorubicin (0.1 μM and 1 μM)." (PMID 19445670, 2009). "We confirmed that both chondrosarcoma cell types expressed P-glycoprotein and antiapoptotic proteins (Bcl-2, Bcl-xL and XIAP)." (PMID 19445670, 2009). "It has already been reported that chondrosarcoma cells highly express P-glycoprotein and antiapoptotic proteins (Bcl-2, Bcl-xL, XIAP)." (PMID 19445670, 2009). "To confirm P-glycoprotein and antiapoptotic protein expression as a possible mechanism of chemoresistance in chondrosarcoma, we measured P-glycoprotein, Bcl-2, Bcl-xL and XIAP expression by immunoblotting." (PMID 19445670, 2009). "siRNA knockdown as well as pharmacologic inhibitors of cell survival proteins (Bcl-2, Bcl-xL and XIAP) enhanced apoptosis of chemoresistant chondrosarcoma cells by up to 5.5 fold at 0.1 μmol and 5.5 fold at 1 μmol doxorubicin." (PMID 19445670, 2009). "Although the role of antiapoptotic proteins in the chemoresistance of chondrosarcoma is not well understood, the overexpression of antiapoptotic proteins (Bcl-2, Bcl-xL, XIAP) is one of the mechanisms of radiation resistance in chondrosarcoma cells." (PMID 19445670, 2009). "BMPR2 in chondrosarcoma stabilizes XIAP, leading to apoptosis resistance." (PMID 30149506, 2018). "We also investigated whether siBMPR2 affects the expression of XIAP of human chondrosarcoma cells in vivo." (PMID 25501832, 2014). "Similarly, we found that downregulation of both BMPR2 and XIAP led to obviously increased cleaved PARP and caspase-3, indicating that inhibition of BMPR2 or XIAP induced apoptosis of chondrosarcoma cells." (PMID 25501832, 2014). "In human chondrosarcoma cells, BMPR2 inhibited apoptosis and autophagy through destabilization of XIAP." (PMID 31889906, 2019). "Jointly, these results demonstrate that apoptosis, mediated by XIAP-caspase-3-PARP, was involved in the response of chondrosarcoma cells to siBMPR2 treatment." (PMID 25501832, 2014).
diffuse large B-cell lymphoma (6 papers, 2015 to 2024). "We show that upregulation of USP9X and consequently of XIAP promote mitotic survival and increased resistance to mitotic spindle poisons in diffuse large B‐cell lymphoma." (PMID 27317434, 2016). "Furthermore, rescue assays were performed to analyze the effects of SNHG5-miR-181-5p-XIAP axis on the biological behaviors of diffuse large B cell lymphoma cells." (PMID 35154447, 2022). "To discern whether the XIAP effect on autophagy is relevant in a cancer context, we assessed LC3-II levels in diffuse large B-cell lymphoma cell lines, where XIAP was reported to be overexpressed and associated with poor clinical outcomes." (PMID 25669656, 2015).
Ewing sarcoma (6 papers, 2016 to 2019). A small round cell tumor that lacks morphologic, immunohistochemical, and electron microscopic evidence of neuroectodermal differentiation. "Here we demonstrate that reconstituting the aqueous and triterpene components from mistletoe in the viscumTT extract synergistically induces caspase-dependent apoptosis associated with CLSPN, MCL1, BIRC5 and XIAP downregulation in Ewing sarcoma cell lines in vitro and primary cells ex vivo." (PMID 27589063, 2016). "Mistletoe extracts also reduced XIAP and BIRC5 expression in Ewing sarcoma cells." (PMID 27589063, 2016). "SOX2 advanced Ewing’s sarcoma cell survival and proliferation by regulating p21, p27 and cyclin-E to facilitate G1/S phase transition and mediating caspase-3, PARP via both extrinsic (Fas and caspase-8) and intrinsic (caspase-9, Bad, Bcl-2 and XIAP) apoptotic pathways to restrain cell apoptotsis." (PMID 26969300, 2016).
head and neck cancer (6 papers, 2012 to 2023). A primary or metastatic malignant neoplasm affecting the head and neck. "Recently, we found that the expression of both cIAP-2 and XIAP appear to be downregulated in head and neck cancer cells treated with anti-lncRNA UCA1 inhibitor." (PMID 31293964, 2019). "A recent study further demonstrated that XIAP is a predictor of chemotherapy response and prognosis for advanced head and neck cancer patients." (PMID 25127132, 2014). "XIAP is a valuable predictor of cisplatin-response and prognosis for patients with advanced head and neck cancer." (PMID 22403616, 2012). "Furthermore, XIAP expression has been correlated, among others, with cisplatin resistance in head and neck cancer." (PMID 36472768, 2023).
rectal cancer (6 papers, 2015 to 2023). A primary or metastatic malignant neoplasm that affects the rectum. "Pre-clinical data from rectal cell lines, human tumors, and murine models have implicated both XIAP and cIAP1/2 in resistance to radiation and chemo-radiation in rectal cancer." (PMID 37686191, 2023). "Increased levels of X-linked inhibitor of apoptosis protein (XIAP) in rectal cancer cells have been found to mediate resistance to neoadjuvant chemoradiotherapy." (PMID 34321074, 2021). "We examined XIAP, cIAP-1, cIAP-2 and Smac protein levels in a cohort of rectal cancer patients to examine whether more chemo resistant tissue displayed an altered protein expression." (PMID 26071313, 2015). "Our data suggests that in the rectal cancer setting those patients who were unresponsive to traditional therapies and displayed high XIAP levels may benefit from Smac mimetic treatment to re-establish the XIAP/Smac balance, and in turn re-sensitise cells to therapy." (PMID 26071313, 2015).
thyroid cancer (6 papers, 2010 to 2022). "Starenki and colleagues demonstrated that inhibition of NF-κB by DHMEQ in thyroid cancer cells induced spontaneous apoptosis through down-regulation of cIAP-1, cIAP-2, and XIAP." (PMID 20492683, 2010). "BRAFV600E could increase the carcinogenicity of thyroid cancer cells through NF-κB mediated c-IAP1, c-IAP2, and XIAP, thus increasing the invasiveness of thyroid cancer cells." (PMID 26985248, 2016). "In vitro experiments showed that XIAP was expressed in the ATC cell lines WRO and SW1736, whereas, no expression of XIAP was detected in the primary cultured follicular cells or the differentiated thyroid cancer cell lines, indicating that XIAP may serve as a specific biomarker of ATC tumors." (PMID 29221164, 2017). "In this study, we showed high XIAP expression in ATC cell lines, but no XIAP expression in the primary cultured follicular cells or the differentiated thyroid cancer cell lines, which was in line with the aberrant XIAP expression found in the invasive area of ATC samples." (PMID 29221164, 2017).
breast tumor (5 papers, 2009 to 2022). "Despite this variability in the cell line panel, XIAP was more markedly upregulated in a subset of the breast tumour samples compared with normal tissue." (PMID 19563669, 2009).
Chediak-Higashi syndrome (5 papers, 2016 to 2025). ChC)diak-Higashi syndrome (CHS) is a rare severe genetic disorder generally characterized by partial oculocutaneous albinism (OCA), severe immunodeficiency, mild bleeding, neurological dysfunction and lymphoproliferative disorder. "Diseases in this group include familial HLH, Chediak-Higashi syndrome, Griscelli syndrome type 2, and X-linked lymphoproliferative disorders such as X-linked inhibitor of apoptosis protein (XIAP) and SH2D1A deficiency." (PMID 40731778, 2025). "Genetic defects predisposing to primary HLH are found in autosomal recessive familial HLH (FHL) 2-5, Griscelli syndrome type 2 (GS2), Chediak-Higashi syndrome (CHS), X-linked lymphoproliferative disease type 1 (XLP1), and X-linked inhibitor of apoptosis (XIAP) deficiency." (PMID 31709205, 2019).
inflammatory breast carcinoma (5 papers, 2009 to 2025). An advanced, invasive breast adenocarcinoma characterized by the presence of distinct changes in the overlying skin. "In inflammatory breast cancer, Trastuzumab treatment was shown to induce an upregulation of XIAP expression." (PMID 19563669, 2009).